OR2J1 (olfactory receptor family 2 subfamily J member 1)
Description:
Odorant receptor.
Synonyms: OR6-5; OR2J1P; hs6M1-4; dJ80I19.2; 6M1-4P; OR6-15
Tractability: Antibody: its Gene Ontology location is reachable by antibodies, with high confidence; UniProt places it where antibodies can reach, with medium confidence; UniProt predicts a signal peptide or a membrane-spanning region.
Gene: Protein-coding gene on chromosome 6 (29,099,490 to 29,102,701, forward strand). Ensembl gene ENSG00000204702.
Subcellular location: Cell membrane
Pathways (Reactome):
Sensory Perception: Expression and translocation of olfactory receptors; Olfactory Signaling Pathway
Gene Ontology:
Molecular function: olfactory receptor activity; G protein-coupled receptor activity
Biological process: detection of chemical stimulus involved in sensory perception of smell; G protein-coupled receptor signaling pathway
Cellular component: plasma membrane; membrane
Genetic constraint (gnomAD): Loss-of-function variants: 7 observed, 7.74 expected, observed/expected ratio (o/e) 0.9, 90% interval 0.51 to 1.64. That is too few expected variants to judge how well the gene tolerates losing a copy. Missense variants: 276 observed, 324.26 expected, observed/expected ratio (o/e) 0.85, 90% interval 0.77 to 0.94. Synonymous variants: 120 observed, 123.55 expected, observed/expected ratio (o/e) 0.97, 90% interval 0.84 to 1.13.
Homologues: Orthologues: chimpanzee OR2J1 (98% identical), mouse Or2j3 (80% identical), rat Or2j3 (80% identical). Paralogues in human: OR2J2 (91% identical), OR2J3 (88% identical), OR2B6 (57% identical), OR2G3 (57% identical), OR2C3 (57% identical), OR2B2 (56% identical), OR2H2 (56% identical), OR2W3 (56% identical), OR2B3 (55% identical), OR2H1 (55% identical), OR2G2 (55% identical), OR2W1 (55% identical), and 80 more.